EGFR (epidermal growth factor receptor)
Diseases named in the same sentence as EGFR in open-access papers (continued):
Sharing a sentence is not in itself a finding about the gene and the disease.
tumor (continued). "The molecular mechanisms through which miR-146a contributes to tumor development are unclear but they seem to be related to the ability of this miRNA to target some mRNAs, such as TRAF6, IRAK1, CXCR4, NF-κB and EGFR." (PMID 24376808, 2013). "Following doxycycline induction, shRNA-mediated silencing of EGFR or Rictor alone was shown to have a small and insignificant impact on U251MG tumor development." (PMID 23555046, 2013). "Importantly, this study enrolls patients whose tumor does not harbor an EGFR activating mutation." (PMID 23555654, 2013). "EGFR and ERBB2 play important roles by dimerizing when their ligands binds to produce downward growth signals to the tumour cells." (PMID 23289484, 2013). "IL-6, EGFR and HSPA8 act as survival factors for neoplasm and increased circulating levels of these proteins have been observed in various types of cancer patients." (PMID 23414419, 2013). "EGFR overexpresses in both cell lines and samples of NSCLC, and contributes to the increased tumor proliferation, poor differentiation, higher incidence of metastases to lymph nodes and a worse prognosis." (PMID 24237755, 2013). "Each combination-inhibition (such as COX-2+EGFR and COX-2+ERBB2) presents a type of therapeutic perturbation for a tumor cell line." (PMID 23967306, 2013). "The HER family of receptors, EGFR/HER1, HER2, HER3, and HER4 are rational targets for anti-cancer drugs because they activate complex signal transduction pathways that lead to tumor cell proliferation, survival, and metastasis." (PMID 26835666, 2013). "We observed the strong amplification of EGFR and neighboring gene IKZF1 in the primary tumor of patient SK01600, but it seems to be partially lost in the matched neurosphere culture." (PMID 23441165, 2013). "The in vivo studies of co-inhibition of EGFR and IGF-1R on the anti-tumor effect of radiotherapy were determined in a nu/nu MDA-MB-468 xenograft mouse model." (PMID 23777562, 2013). "Patient and primary tumor characteristics (estrogen receptor (ER), progesterone receptor (PR), HER2, EGFR, and Ki67) were evaluated." (PMID 24490077, 2013). "The antineoplastic activity of CIK cells directed by the EGFR/CD3 BsAb was analyzed with tumor growth and tumor reduction assays." (PMID 23833649, 2013). "A similar phenomenon has been described for other RTKs such as EGFR, ErbB2, ErbB3, ErbB4 and VEGFR2 where truncated versions had functional implications for the growth of the tumor cells." (PMID 24205204, 2013). "By targeting HER2 through different molecular mechanisms, EGFR inhibitors, and particularly HER2 inhibitors (including trastuzumab and the dual EGFR/HER2 inhibitor lapatinib), inhibit tumor growth, and induce apoptosis." (PMID 24069582, 2013). "In athymic nude mice implanted with EGFR and VEGFR2 overexpressing NSCLC cells, delphinidin treatment resulted in significant inhibition of tumor growth." (PMID 24124611, 2013). "The chimeric IgG1 therapeutic antibody cetuximab targets EGFR in colorectal cancer (CRC) and has like trastuzumab ADCC and abrogation of tumor cell signaling as the modes of action." (PMID 23543707, 2013). "In previous randomized studies comparing EGFR TKI therapy to regular chemotherapy, the proportion of patients with adequate tumor tissue for analysis ranged from 10 to 38%." (PMID 23922984, 2013). "Tumor tissue that contained increased mature and active COX-2 (74 kDa) protein seemed to lack epidermal growth factor receptor (EGFR) protein." (PMID 24171795, 2013). "Since EGFR, a key mediator of angiogenesis, can regulate its target genes such as VEGF, which can directly affect tumor biological behavior." (PMID 23555641, 2013).
tumor (continued). "We sought to analyze which EGFR- and STAT3-activating factors are secreted by monocytes/macrophages exposed to tumor cell-secreted factors." (PMID 23597096, 2013). "We also observed that EGFR TKI-sensitive and -resistant clinical NSCLC tumor specimens had higher total and phosphorylated p70S6K expression levels." (PMID 23874880, 2013). "EGFR and ERBB2 were also both found to be significantly up-regulated in all r4 subgroups as well as in the GNB and GN tumours." (PMID 23835063, 2013). "Our main focus was on the paracrine release of both EGFR and STAT3 activators by monocytes/macrophages to tumor cells." (PMID 23597096, 2013). "EGFR, like HER2, is a potent stimulating factor of cell-growth-activating pathways and thus stimulates tumor growth when activated." (PMID 24490077, 2013). "Accordingly, in a xenograft mouse model, VPA/HU efficiently blocked tumor growth (P<0.001) correlating with BIM induction and EGFR downregulation." (PMID 22289787, 2012). "As an adaptor protein, EBP50 can interact with multiple types of proteins to exert tumor-promoting or tumor-suppressing functions by influencing multiple signaling pathways, including Wnt, AKT, platelet-derived growth factor receptor (PDGFR), EGFR, and ERK1/2." (PMID 22476347, 2012). "In experimental models, the use of an EGFR TKI in combination with RT has been shown to increase antitumor activity by amplifying radiation-induced apoptosis and inhibiting tumor angiogenesis." (PMID 23110940, 2012). "The fact that tumor cells respond to HGF with increased proliferation and survival following EGFR inhibition has also been addressed in non-small cell lung cancer (NSCLC)." (PMID 23028720, 2012). "The human epidermal growth factor family of receptors (HER1/EGFR, HER2, HER3, and HER4) plays an important role in the proliferation, differentiation, and transformation of tumor cells." (PMID 25031970, 2012). "Over-expression of EGFR played an important role in tumour initiation and progression of RCC; thus, the up-regulation of EGFR was correlated with high-grade tumours and a worse prognosis." (PMID 22937740, 2012). "Stimulated by EGFR or HER2, PI3K activates the Ser/Thr kinase AKT, thus promoting cell survival and tumour growth." (PMID 22240798, 2012). "In view of the important role of STAT3/EGFR signaling in tumor development and progression, the methods to inhibit EGFR in conjunction with oncogenic STATs may represent a novel and attractive therapeutic strategy for cancers characterized by upregulation of EGFR signaling." (PMID 23118721, 2012). "We studied the correlation between mean ADC value and prognostic factors such as tumor size, LN metastasis, histologic grade, age, and expression levels of ER, PR, HER2, EGFR, and Ki-67." (PMID 22741544, 2012). "We previously validated the use of TR-FRET for the analysis of HER dimers in stably transfected NIH/3T3 cell lines that express EGFR and/or HER2 and in various tumor cell lines." (PMID 22829865, 2012). "The Basal subtype was a BRCAX tumour with prominent CK5 and EGFR staining but also low ER nuclear positivity." (PMID 23146383, 2012). "Interestingly, the Therascreen EGFR Mutation Test kit was able to characterize as wild-type one tumour that could not be analyzed by direct sequencing of the PCR product." (PMID 22952784, 2012). "The activation of EGFR signaling, such as Ras/Raf/MAP/MEK/ERK and/or PTEN/PI3K/Akt pathways, plays an important role in tumorigenesis and the tumor progression of CRC." (PMID 22043994, 2012). "The recognition of HER3 as a co-inducer of tumour development, as well as its importance in the context of resistance against HER2 or EGFR-targeted therapies, has lead to increased efforts in finding a way to block the activity of this receptor." (PMID 22768204, 2012).
tumor (continued). "Xenograft human tumor tissue (n = 10) of non-small cell lung cancer (NSCLC) origin and NSCLC patient tumor tissue samples (n = 23) were microdissected and the EGFR-SRM assay performed on Liquid Tissue lysates prepared from microdissected tissue." (PMID 22554165, 2012). "Tumor tissues derived from J cells exhibited high expression levels of HIF-2α and EGFR compared to the slow developing and small K cell derived tumors." (PMID 22768190, 2012). "To this aim, first, we tried to estimate by fluorescence-activated cell sorting (FACS) the number of receptors per cell in cell suspensions obtained by dissociation of NIH/3T3 EGFR, NIH/3T3 HER2, NIH/3T3 EGFR/HER2 and SKOV-3 tumor xenografts." (PMID 22829865, 2012). "Finally, the touchdown PCR and melting conditions of this DPYD HRM assay were suitable for analysis of KRAS, BRAF, and EGFR somatic hotspot mutations in tumor samples (not shown), thus enabling simultaneous analysis of relevant mutations for targeted cancer therapy." (PMID 23335937, 2012). "In the tumor specimens obtained by surgical resection, the expression levels of the GPR30, EGFR, ERα and ERβ proteins were evaluated." (PMID 23163984, 2012). "Epidermal growth factor receptor (EGFR) is a member of the c-ERB-B family of tyrosine kinase receptor proteins, and has a role in tumor cell survival and proliferation." (PMID 23082819, 2012). "For instance, display of recombinant Affibody libraries has generated EGFR- and HER2-specific Affibody molecules, which have shown promising results for both tumour imaging and therapeutic applications." (PMID 22768204, 2012). "Comparing SRM data to the previous EGFR analyses indicates SRM results consistent with both western blot and SRM analysis of the matched frozen tumor tissue and show a correlative trend to IHC data of the FFPE tumors." (PMID 22554165, 2012). "In contrast, blocking FXR activation increases Src (Tyr416) phosphorylation, which in turn activates EGFR and post-receptor ERK1/2 signaling, thereby resulting in increased cell proliferation and tumor growth." (PMID 23119029, 2012). "Since EGFR and AKT are involved in various aspects of cancer growth ranging from tumor initiation, angiogenesis, and metastasis, EGFR-AKT axis represents an attractive target for therapeutic intervention." (PMID 22952709, 2012). "The epidermal growth factor receptor (EGFR) and K-ras are two such targets that can help classify tumours on a molecular basis and guide treatment decisions." (PMID 22666589, 2012). "We also know from investigations of the relationship between PTPRJ and EGFR, that one proposed tumour suppressive mechanism for DEP-1 is the inactivation and retention of EGFR at the cell membrane and therefore the abrogation of EGF-induced signaling." (PMID 22815804, 2012). "Endocrine-resistant tumor cells display upregulation of IGF-1R, HER2, and EGFR levels, as well as increased PI3K/AKT/mTOR activation." (PMID 23344024, 2012). "As a consequence, necitumumab inhibits downstream targets in the EGFR pathway (e.g., MAPK) inhibiting proliferation of EGFR-dependent tumor cells." (PMID 22754305, 2012). "EGFR from tumor-derived microvesicles can also be transferred to endothelial cells, eliciting VEGF upregulation and tumor angiogenesis." (PMID 22738135, 2012). "EGFR is activated by the ligand EGF which in turn activates multiple cell signaling pathways and modulates tumor cell division, invasion and apoptosis." (PMID 22918789, 2012). "Taken together, these results validate our TR-FRET assays for the absolute quantification of EGFR and HER2 expression in tumor samples." (PMID 22829865, 2012).
tumor (continued). "Results were correlated to clinicopathological parameters, long-term survival, epidermal growth factor receptor (EGFR) and human epidermal growth factor receptor 2 (HER2) (IHC and FISH) status of the tumours." (PMID 22240798, 2012). "Given their prominent role in tumour growth, invasion, and metastasis, the VEGFR and EGFR signaling pathway present feasible targets for pharmacologic intervention in NSCLC, and several agents have demonstrated encouraging antitumor activity." (PMID 22916093, 2012). "In the bulk of HEp3 tumors α5β1 integrins are activated by the urokinase receptor (uPAR) to recruit focal adhesion kinase and EGFR to activate ERK1/2 signaling and tumor growth." (PMID 22276135, 2012). "Such absolute quantification allows comparing the expression levels of EGFR and HER2 in the same tumor." (PMID 22829865, 2012). "In this work, for model antibodies (as a targeting module), we chose anti-tumor 425scFv and 4D5scFv, which selectively bind to oncomarkers HER1/EGFR and HER2/neu, respectively." (PMID 23133578, 2012). "A panel of tumor-specific markers (GLUT1, EGFR, HER2, IGF1-R, MET, and CAIX) was in the present study able to 'detect' 45.5% of all cancers and 55.6% of ductal cancers." (PMID 22695343, 2012). "Panitumumab is a fully human monoclonal antibody that binds EGFR with high affinity (5x10-11 M), prevents ligand-induced activation of all EGF-like ligands and production of angiogenic factors, and arrests tumor cell proliferation." (PMID 22830443, 2012). "The most widely expressed tumor-specific protein in our cohort was GLUT1, positive in 20.3% of the cancers, followed by EGFR (17.4%), IGF-1R (12.8%), HER2 (10.4%), CAIX (9.5%), and MET (8.9%)." (PMID 22695343, 2012). "The NIH/3T3 EGFR, NIH/3T3 HER2, NIH/3T3 EGFR/HER2 and SKOV-3 tumor xenograft models were used as calibrators for the HER quantification assays in order to convert the TR-FRET signal into the number of receptors per cell." (PMID 22829865, 2012). "We developed TR-FRET-based assays for the accurate quantification of EGFR and HER2 expression in tumor cryosections, as well as assays for the assessment of their activation though the quantification of receptor homo- or hetero-dimerization." (PMID 22829865, 2012). "Harvested primary mammary fat pad tumor tissue was immunohistochemically stained for CK18, EGFR and Her2 expression." (PMID 23118918, 2012). "To quantify the absolute amount of EGFR and HER2 using the HER quantification TR-FRET assays, we used the tumor xenograft models as calibrators to convert the fluorescence signal measured by TR-FRET analysis into the number of receptors per cell." (PMID 22829865, 2012). "Including TfR, Mammaglobin, and MUC1 to the panel of highly tumor-specific markers GLUT1, MET, EGFR, IGF1-R, CAIX, and HER2 increased the detection rate from 45.5% to 49.8% (TfR), 56.4% (Mammaglobin), and 98.1% (MUC1), respectively." (PMID 22695343, 2012). "We observed that TGFα, via EGFR, promoted proliferation of KGN and COV434 cells and facilitated KGN tumor cell migration." (PMID 23155381, 2012). "TAGCNA identifies SCEs that are known to be involved with proto-oncogenes (e.g. EGFR, CDK4) and tumor suppressor genes (e.g. CDKN2A, CDKN2B), and provides many additional SCEs with potential biological relevance in these data." (PMID 22815924, 2012). "Expression of GLUT-1, EGFR, MMP-9 and Cathepsin B was found throughout the tumor and the expression patterns closely corresponded to those obtained with FLI." (PMID 22348134, 2012). "Antibodies against the epidermal growth factor receptor (EGFR), cetuximab and panitumumab, have shown a survival benefit in mCRC patients with KRAS wild-type tumours both as monotherapy and when added to chemotherapy." (PMID 22804917, 2012).
tumor (continued). "This EGFR-SRM assay represents a highly promising approach to quantitating and monitoring EGFR levels in patient tumor tissue." (PMID 22554165, 2012). "Immunohistochemical detectability of EGFR, IGF-1R, and phospho-HER2 in our study was the best for tissue fixed with standard formalin throughout all xenograft tumor models." (PMID 22814649, 2012). "FXR activation results in inactivation of Src and EGFR, thereby inhibiting post-EGFR ERK1/2 signaling and attenuating cell proliferation and tumor growth." (PMID 23119029, 2012). "We examine a number of factors including clinicopathological features of the primary tumour, lymph node metastasis, and the CCND1 and EGFR gene status of primary tumours, and evaluate the value of predicting the risk of ECS of metastatic lymph nodes." (PMID 21304522, 2011). "EGFR is commonly elevated in many advanced cancers, and VEGFR2 is considered one of the key regulators of tumor-induced angiogenesis." (PMID 21943352, 2011). "Thus, EGFR-TKIs and chemotherapy may result in a sequence-dependent tumor regression." (PMID 21366910, 2011). "In conclusion, we demonstrated a high level of concordance of 96.4% between primary tumours and liver metastases, which for clinical purposes to select CRC patients for anti-EGFR therapy was even higher with 98%." (PMID 21364579, 2011). "Two representative genes, EGFR and TH1L, were illustrated to demonstrate the high correlations between copy number and gene expression in tumor tissues." (PMID 21935476, 2011). "Considering the presented results, the number of EGFR-specific CTL before and after tumor therapy in correlation to the frequency of regulatory T cells would be of high interest and will be addressed in future longitudinal studies." (PMID 21970318, 2011). "Not only, this study throws light on the molecular blue print that underlies after clinical doses of IR in HNSCC, this study also identifies the potential of the EGFR TK, EKB-569 in selectively targeting IR-induced NFκB and subsequent tumor progression." (PMID 22242139, 2011). "Activation of EGFR induces activation of intracellular STAT, MAPK, PI3K and PLC pathways, leading to tumor cell proliferation, angiogenesis, cell migration and a decreased rate of apoptosis." (PMID 21970318, 2011). "As EGFR is a self-antigen, the frequency of EGFR-specific CTL is expected to be low in the peripheral blood of HNSCC patients, and the ability of these cells to recognize EGFR+ tumor cells to be weak." (PMID 21970318, 2011). "Because the EGFR alteration was also stably retained in sc serial passaging of GBM xenografts, it is clear that flank tumor gene alteration was maintained following tumor transfer to the orthotopic setting." (PMID 21314332, 2011). "Constitutive activation of signaling via EGFR, MAPK and PI3K pathways can promote uncontrolled cell growth, tumor cell survival as well as resistance to cytotoxic agents." (PMID 21738740, 2011). "Stable suppression of EGFR by shRNA prevents serum-free growth of VHL-defective ccRCC cells in vitro, and retards the tumor growth of these cells for extended periods in xenograft models, without affecting HIF2αfunctions." (PMID 21949687, 2011). "A further aim was to investigate the effects of blocking the epidermal growth factor receptor (EGFR) and its downstream pathways (Raf/MEK/ERK, PI3K/Akt) on tumor cell migration in vitro." (PMID 21896192, 2011). "More interesting, this study outlined the ability of anti-EGFR antibodies to target the CD133+ CSC population, acting as radiosensitizers in this tumor model." (PMID 24212957, 2011). "Expression of the EGFR is up regulated in CRPC suggesting that growth of these late stage tumours is at least in part driven by exaggerated signaling through the EGFR." (PMID 22193779, 2011). "However, how TNBCs enrich for tumor cells with high EGFR expression is unknown." (PMID 21396117, 2011).